PDLIM2 (PDZ and LIM domain 2)
Diseases named in the same sentence as PDLIM2 in open-access papers (continued):
Sharing a sentence is not in itself a finding about the gene and the disease.
colorectal cancer (2 papers, 2017 to 2025). A primary or metastatic malignant neoplasm that affects the colon or rectum. "In vivo experiments in mice have also demonstrated that PDLIM2 can reduce the tumorigenicity of colorectal cancer cell lines, thereby providing a potentially promising therapeutic target for colorectal cancer drug discovery." (PMID 40476213, 2025). "Previous studies have shown that treatment of colorectal cancer cell lines with DNA methyltransferase inhibitors rescues PDLIM2 expression, leading to inhibition of NF-κB activation in a dose-dependent manner and a subsequent reduction in tumor growth." (PMID 40476213, 2025).
diffuse large B-cell lymphoma (2 papers, 2021 to 2022). "High PDLIM2 expression was also correlated with a longer DFI in lymphoid neoplasm diffuse large B-cell lymphoma (P = 0.016) and LUAD (P = 0.026)." (PMID 35121770, 2022). "PDLIM2 expression was positively correlated with MSI in breast invasive carcinoma, diffuse large B-cell lymphoma, and thyroid carcinoma." (PMID 35121770, 2022).
esophageal cancer (2 papers, 2022 to 2023). A primary or metastatic malignant neoplasm involving the esophagus. "Multiple cancer types exhibited a significant association between patient prognosis and PDLIM2 expression, including breast, kidney, blood, brain, and esophageal cancer." (PMID 35121770, 2022). "Higher PDLIM2 expression was observed in breast invasive carcinoma, esophageal carcinoma, glioblastoma multiforme, pheochromocytoma, and paraganglioma." (PMID 35121770, 2022).
idiopathic pulmonary fibrosis (2 papers, 2025). Idiopathic pulmonary fibrosis (IPF) is a nonneoplastic pulmonary disease that is characterized by the formation of scar tissue within the lungs in the absence of any known cause. "Gene expression data on human samples were exploited to investigate if PDLIM2 is repressed in the lung of patients with chronic obstructive pulmonary disease (COPD) or interstitial lung disease (ILD/idiopathic pulmonary fibrosis (IPF)." (PMID 41346604, 2025). "The pathological activation of lung fibroblasts in COVID-19 patients involved intrinsic PDLIM2 repression, Because the NF-κB, STAT3, cellular stress, pulmonary fibrosis, pathogen-induced cytokine storm." (PMID 41000764, 2025).
influenza (2 papers, 2011 to 2025). An acute viral infection of the respiratory tract, occurring in isolated cases, in epidemics, or in pandemics; it is caused by serologically different strains of viruses (influenzaviruses) designated A, B, and C, has a 3-day incubation period, and usually lasts for 3 to 10 days. "Same as in neutrophils, PDLIM2 expression was repressed in monocytes from influenza patients compared to those from uninfected healthy humans; and this repression was associated with ultra-activation of NF-κB and STAT3." (PMID 41000764, 2025). "Despite these limitations, our study presents valuable biomarker discovery, underscoring the need for future prospective studies to validate the prognostic value of PDLIM2 expression in viral infectious diseases, especially influenza and COVID-19." (PMID 41000764, 2025). "Indeed, PDLIM2 expression was significantly lower in neutrophils from influenza patients in comparison to those from uninfected healthy people." (PMID 41000764, 2025). "In summary, our study demonstrates that low PDLIM2 expression in the context of influenza and COVID-19 correlates with unfavorable molecular and cellular profiles of pro-inflammation and pro-fibrosis and cell injury, and is associated with increased disease severity." (PMID 41000764, 2025).
lung disease (2 papers, 2024 to 2025). "However, whether PDLIM2 plays a broader role in other lung diseases remains unclear." (PMID 41346604, 2025).
non-small cell lung carcinoma (2 papers, 2022 to 2025). A group of at least three distinct histological types of lung cancer, including non-small cell squamous cell carcinoma, adenocarcinoma, and large cell carcinoma. "PDLIM2 plays a role as a tumor suppressor gene in non-small cell lung cancer by down-regulating the NF-κB signaling pathway." (PMID 34713769, 2022). "Similarly, PDLIM2 exhibits low expression in non-small cell lung cancer, leading to the restricted proliferation and invasion of non-small cell lung cancer (NSCLC) cells, as well as other malignant behaviors." (PMID 40476213, 2025).
renal carcinoma (2 papers, 2021 to 2022). A carcinoma arising from the epithelium of the renal parenchyma or the renal pelvis. "In this study, we evaluated the expression pattern of PDLIM2 in human renal cancer cells and metastatic kidney cancer and the effect of PDLIM2 inhibition on tumor growth and invasiveness." (PMID 34203785, 2021).
rheumatoid arthritis (2 papers, 2022 to 2025). A chronic, systemic autoimmune disorder characterized by inflammation in the synovial membranes and articular surfaces. "RT-qPCR and Western blot detected the expressions of PDLIM2 and KLF10 in Human Rheumatoid arthritis FLSs (HFLSs-RA)." (PMID 34713769, 2022).
Sepsis (2 papers, 2024 to 2025). Sepsis is defined as life-threatening organ dysfunction caused by a dysregulated host response to infection. "In detail, Vangl2 functions as an adaptor protein to recruit an E3 ubiquitin ligase PDLIM2 to increase K63-linked ubiquitination of p65 and promotes NDP52-mediated p65 degradation through selective autophagy, resulting in ameliorating sepsis and suppressing production of proinflammatory cytokines." (PMID 39269442, 2024). "However, the latest research has found that in the lipopolysaccharide (LPS)-induced sepsis model, van Gogh-like protein 2 (VANGL2) recruits PDZ and lim domain protein 2 (PDLIM2) to catalyze the K63-type ubiquitination of p65." (PMID 40643532, 2025).
viral infection (2 papers, 2019 to 2025). "We found that PDLIM2 expression was repressed by viral infection, and notably, this repression correlated with the severity of infectious diseases." (PMID 41000764, 2025). "Since PDLIM2 was shown to act in the nucleus following NF-κB activation, we investigated the effects of viral infection on PDLIM2 expression in the human hepatocyte cell line Huh7.5." (PMID 31374104, 2019). "While its role in cancer is established, the involvement of PDLIM2 in viral infection remains unclear." (PMID 41000764, 2025). "Together, these results indicate viral infection leads to induction of PDLIM2, a non-ISG which targets key signal transduction intermediates such as STATs and NF-κB for degradation, and may be a common mechanism whereby flaviviruses inhibit the host interferon response." (PMID 31374104, 2019).
Zika virus infection (2 papers, 2019). "Expression of PDLIM2 mRNA increased 14 fold after Zika virus infection, and was dependent on the amount of initial inoculum." (PMID 31374104, 2019). "PDLIM2–/– Huh7.5 cells were more resistant to HCV, DENV, and ZIKV infection than parental cells." (PMID 31652496, 2019).
bladder cancer (1 paper, 2022). "Notably, PDLIM2 expression was strongly correlated with TIM-3 in bladder cancer and with PDCD1, CTLA4, GZMB, and LAG3 in KIRP." (PMID 35121770, 2022).
breast tumour (1 paper, 2022). "Here, we established that high PDLIM2 expression in breast tumour cells is associated with infiltration of an M2 macrophage population, and that PDLIM2 is required for full polarization of M2 macrophages in vitro." (PMID 36531051, 2022). "In this TMA (approximately 250 cores), more than 70% of PDLIM2-positive tumours exhibited PDLIM2 expression in the stroma compared to PDLIM2-negative breast tumours where PDLIM2 was present in only 30% of stromal cells." (PMID 36531051, 2022). "Our analysis of PDLIM2 expression in breast tumour tissue suggests that its presence may favour the expansion of the M2 macrophage population." (PMID 36531051, 2022). "Thus, PDLIM2 could identify tumours with M2 macrophage function and thereby increase our knowledge of immune cell interactions in the breast tumour microenvironment, which may be particularly useful for new therapy options in TNBC." (PMID 36531051, 2022). "Taken together, these data demonstrate that in all breast tumours that exhibit expression, PDLIM2 is also highly expressed in the stroma, while TNBC displays high PDLIM2 in the stroma of all tumours." (PMID 36531051, 2022).
cholangiocarcinoma (1 paper, 2022). A carcinoma that arises from the intrahepatic biliary tree (intrahepatic cholangiocarcinoma) or from the junction, or adjacent to the junction, of the right and left hepatic ducts (hilar cholangiocarcinoma). "PDLIM2 was negatively correlated with the TMB in BLCA, cholangiocarcinoma, COAD, LIHC, LUAD, LUSC, paraganglioma, prostate adenocarcinoma, pulmonary enteric adenocarcinoma, stomach adenocarcinoma, and thymoma and positively correlated with ACC." (PMID 35121770, 2022).
Cirrhosis (1 paper, 2019). A chronic disorder of the liver in which liver tissue becomes scarred and is partially replaced by regenerative nodules and fibrotic tissue resulting in loss of liver function. "The consequences of dysregulated PDLIM2 expression may range from inflammatory conditions, which during HCV infection, leads to fibrosis and cirrhosis, to the development of tumors in the affected cells." (PMID 31374104, 2019).
colon adenocarcinoma (1 paper, 2022). "The expression level of PDLIM2 was positively correlated with immune infiltrates, including B cells, CD8+ T cells, CD4+ T cells, neutrophils, macrophages, and dendritic cells in bladder urothelial, kidney renal papillary cell, and colon adenocarcinoma." (PMID 35121770, 2022).
COVID-19 (1 paper, 2025). A disease caused by infection with severe acute respiratory syndrome coronavirus 2. "Mechanistically, we found that PDLIM2 was repressed in the AECs of COVID-19 patients, associating with increased NF-κB, STAT3, cell cycle checkpoints, senescence, clathrin-mediated endocytosis (CME), and pro-inflammatory cytokines but decreased RhoGDI and PPAR signaling pathways." (PMID 41000764, 2025). "Like AT2 cells, AT1 cells in COVID-19 patients had a PDLIM2 repression-dependent hyper-activation of NF-κB and STAT3." (PMID 41000764, 2025). "Same as myeloid cells, T cells in COVID-19 patients expressed PDLIM2 at a much lower level and had high NF-κB and STAT3 activation." (PMID 41000764, 2025). "immunogenic cell death and cyclophilin signaling pathways were significantly higher, while the RhoGDI, PPAR and inhibition of matrix metalloproteases (MMPs) signaling pathways were lower in PDLIM2-low lung fibroblasts of COVID-19 patients." (PMID 41000764, 2025).
Dengue virus infection (1 paper, 2019). "Dengue virus infection had the most dramatic effect on PDLIM2 expression with a 20 fold increase in PDLIM2 expression soon after infection followed by a rapid decline, again in a MOI dependent manner." (PMID 31374104, 2019). "We found that HCV, Zika virus, and Dengue virus infections upregulated PDLIM2 in a dose and time dependent manner, but not in an interferon dependent manner." (PMID 31374104, 2019).
Flavivirus Infections (1 paper, 2019). Infections with viruses of the genus FLAVIVIRUS, family FLAVIVIRIDAE. "This study also showed that knockout of PDLIM2 resulted in less efficient IFN-α-mediated STAT2 degradation; however, STAT2 degradation during flavivirus infection was not investigated in PDLIM2–/– cells." (PMID 31652496, 2019).
glomerulopathies (1 paper, 2021). "Pdlim2 was already shown to be essential for the stability of the actin cytoskeleton in cultured podocytes as well as was regulated in patients suffering from glomerulopathies." (PMID 34879092, 2021).
Insulin resistance (1 paper, 2025). Increased resistance towards insulin, that is, diminished effectiveness of insulin in reducing blood glucose levels. "PDLIM2 expression is downregulated in steatohepatitis, and experimental evidence has demonstrated that deletion of the PDLIM2 gene promotes hepatic dyslipidemia and exacerbates insulin resistance in mice." (PMID 40476213, 2025).
intestinal cancer (1 paper, 2025). "Epigenetic inhibition of PDLIM2 leads to reduced expression across various intestinal cancer cell lines, indicating that the loss of PDLIM2 is a significant contributor to NF-κB activation, with epigenetic inhibition being associated with promoter methylation." (PMID 40476213, 2025).
kidney cancer (1 paper, 2021). Primary or metastatic malignant neoplasm involving the kidney. "PDLIM2 protein expression was higher in the locally advanced state and the metastatic stage kidney cancer cells than in the early stage." (PMID 34203785, 2021). "Our results indicate that PDLIM2 inhibition can effectively inhibit tumor growth and metastasis in a orthotopic kidney cancer formation model." (PMID 34203785, 2021). "This is the first study to examine the role of PDLIM2 in the tumor growth and metastasis of kidney cancer in a xenograft model." (PMID 34203785, 2021). "PDLIM2 was overexpressed in various kidney cancer cell lines of metastatic origin, such as Caki1 and ACHN, compared to those of primary origin." (PMID 34203785, 2021). "Our results indicate that PDLIM2 inhibition can effectively inhibit lung tumor formation in experimental metastasis model of kidney cancer cells xenograft model." (PMID 34203785, 2021). "We evaluated the expression of PDLIM2 in human kidney cancer cell lines from primary or metastatic origins and found that PDLIM2 expression was highly elevated in metastatic kidney cancers." (PMID 34203785, 2021). "In the present study, a decreased migration ability of metastatic kidney cancer cells was observed in the PDLIM2 knockdown group, in which PDLIM2 was selectively inhibited." (PMID 34203785, 2021). "As metastasis adaptation characteristics were acquired in murine kidney cancer cell line, PDLIM2 expression also was increased." (PMID 34203785, 2021). "In particular, the specific inhibition of PDLIM2 was found to result in the reduced proliferation and migration ability of metastatic kidney cancer cells." (PMID 34203785, 2021). "In a cancer genome atlas analysis, PDLIM2 was reported to be an unfavorable prognostic factor in kidney cancer." (PMID 34203785, 2021). "The inhibition of PDLIM2 decreases the invasion capacity and proliferation of kidney cancer cells and the production of crones." (PMID 34203785, 2021). "PDLIM2 is highly expressed in highly metastatic kidney cancer." (PMID 34203785, 2021). "In addition, we evaluated the in vivo efficacy of PDLIM2 knockout on the tumor formation and metastasis of kidney cancer cells using a PDLIM2 knockout mice." (PMID 34203785, 2021). "In addition, we provide in vivo evidence that the specific inhibition of PDLIM2 significantly reduces tumor growth and metastasis in a human kidney cancer xenograft model; this is the key finding of our study." (PMID 34203785, 2021). "PDLIM2 was overexpressed in various stages of human kidney cancer cells." (PMID 34203785, 2021). "Based on these results, we hypothesized that PDLIM2 can act as a metastasis-related oncogenic protein in kidney cancer." (PMID 34203785, 2021). "To confirm whether PDLIM2 acts as an oncogene in human kidney cancer cells, we generated PDLIM2 knockdown stable human metastatic kidney cancer cell lines (shRNA-expressing Caki-1 cell lines; Sh_PDLIM2_01 and Sh_PDLIM2_02) using short hairpin RNA (shRNA) in Caki-1 cells and ACHN." (PMID 34203785, 2021). "We observed that PDLIM2 is expressed at high levels in metastatic human kidney cancer cell lines comparing non-metastatic kidney cancer cell lines." (PMID 34203785, 2021).
kidney tumors (1 paper, 2021). "We first observed PDLIM2 protein expression in kidney tumors injected with original (M0) and metastatic (M1,M2) RenCa cells." (PMID 34203785, 2021).
Lewis lung carcinoma (1 paper, 2024). "A Lewis lung carcinoma (LLC) mouse model was established to assess the in vivo function of PDLIM2 and HIF-1α." (PMID 38880883, 2024).
liver cancer (1 paper, 2024). An epithelial or non-epithelial malignant neoplasm that arises from the liver. "Additionally, PDLIM2, known as a tumor suppressor, exhibits low expression in liver cancer tissues." (PMID 38992675, 2024).
lymph node metastasis (1 paper, 2022). "As seen by clinical correlation analysis, the reason for this discrepancy may be that high PDLIM2 expression contributes to the poor prognosis of LUSC patients by affecting lymph node metastasis." (PMID 35121770, 2022).
melanoma (1 paper, 2025). A malignant, usually aggressive tumor composed of atypical, neoplastic melanocytes. "Future studies on PDLIM2 or Regnase-1 and -3 might provide insights into the mechanism of constitutive IκBζ expression in melanoma cells." (PMID 40562773, 2025).
multiple sclerosis (1 paper, 2012). A progressive autoimmune disorder affecting the central nervous system resulting in demyelination. "Notably, PDLIM2 deficient mice exhibited increased susceptibility to experimental autoimmune encephalitis (EAE), a Th1 and/or Th17 cell-mediated inflammatory disease model of multiple sclerosis (MS)." (PMID 22731402, 2012).
ovarian serous cystadenocarcinoma (1 paper, 2022). A malignant serous cystic epithelial neoplasm arising from the ovary. "High PDLIM2 expression levels were associated with a shorter DFI in KIRP (P = 0.023), prostate adenocarcinoma (P = 0.026), and ovarian serous cystadenocarcinoma (P = 0.012)." (PMID 35121770, 2022).
periodontitis (1 paper, 2025). An acute or chronic inflammatory process that affects the tissues that surround and support the teeth. "E3s, including Cullin3 (CUL3), Nedd4‐2, Synoviolin, FBXL19, PDLIM2, TRIMs and TRAFs have been identified as key players in modulating periodontitis." (PMID 39626954, 2025). "Regarding the protective role of PDLIM2, targeted activation of PDLIM2 in osteocytes may offer a promising therapeutic approach for periodontitis." (PMID 39626954, 2025). "Increasing evidence indicated that E3s, such as CUL3, Nedd4‐2, Synoviolin, FBXL19, PDLIM2, TRIMs and TRAFs, modulate inflammatory responses and bone resorption in periodontitis through multiple classical signalling pathways, including NLRP3, GSDMD, NF‐κB, Wnt/β‐catenin and Nrf2." (PMID 39626954, 2025).
primary effusion lymphoma (1 paper, 2021). A large B-cell lymphoma located in the body cavities, characterized by pleural, peritoneal, and pericardial fluid lymphomatous effusions and that is always associated with human herpes virus-8 (HHV-8). "Transcription repression via CpG DNA hyper-methylation of p16INK4a (CDKN2A), the TGF-beta type II receptor (TbetaRII, TGFBR2), and PDZ-LIM domain-containing protein 2 (PDLIM2) promoters have been detected in KSHV-infected primary effusion lymphoma (PEL) lines." (PMID 34307191, 2021).
renal cell carcinoma (1 paper, 2022). "A recent study revealed that PDLIM2 was highly correlated with tumor growth and metastasis in renal cell carcinoma in a mouse knockout model." (PMID 35121770, 2022).
serous ovarian carcinoma (1 paper, 2016). "We determined PDLIM2 levels in normal ovary, fallopian tube, and high grade serous ovarian carcinoma (HGSC) specimens." (PMID 26593252, 2016).
thymic carcinoma (1 paper, 2022). Thymic carcinoma (TC) is a type of thymic epithelial neoplasm characterized by a high malignant potential. "We also observed significant correlations between PDLIM2 expression and patient survival in thymic carcinomas, which has not been widely reported in previous studies." (PMID 35121770, 2022).
thymoma (1 paper, 2022). A neoplasm arising from the epithelial cells of the thymus. "In contrast, reduced PDLIM2 expression was correlated with poor prognosis in thymoma (P = 0.04)." (PMID 35121770, 2022).